RBBP7 (RB binding protein 7, chromatin remodeling factor)
Diseases named in the same sentence as RBBP7 in open-access papers (continued):
Sharing a sentence is not in itself a finding about the gene and the disease.
Sepsis (1 paper, 2025). Sepsis is defined as life-threatening organ dysfunction caused by a dysregulated host response to infection. "One bioinformatic analysis showed that RBBP7 can be used as a biomarker for sepsis, and the reported change trend was the same as ours." (PMID 41394771, 2025). "The mRNA expression of ATP11B was upregulated and that of RBBP7 was downregulated in LPS‐induced sepsis, in line with our bioinformatic analysis results." (PMID 41394771, 2025). "Based on our bioinformatic and experimental findings, we further explored the therapeutic potential of ATP11B and RBBP7 within sepsis pathophysiology." (PMID 41394771, 2025). "The mRNA expression of ATP11B was increased, but RBBP7 was downregulated in LPS‐induced sepsis, aligning with the findings from the bioinformatic study." (PMID 41394771, 2025). "In contrast, RBBP7 is downregulated in sepsis and demonstrates positive correlations with activated NK cells and memory CD4+ T cells." (PMID 41394771, 2025). "This work demonstrated that mRNA expressions of ATP11B were significantly elevated and those of RBBP7 were significantly decreased in LPS‐induced sepsis, aligning with the findings of bioinformatic analysis." (PMID 41394771, 2025). "Collectively, our bioinformatic and experimental findings indicate that ATP11B, RBBP7, DOCK10, and NUP160 are implicated in the pathogenesis and progression of sepsis." (PMID 41394771, 2025). "Our research shows that ATP11B and RBBP7 emerge as validated, promising biomarkers for sepsis, supported by consistent upregulation/downregulation in both bioinformatics and experimental models." (PMID 41394771, 2025). "ATP11B, RBBP7, DOCK10, and NUP160 may play the major role in the occurrence and progression of sepsis." (PMID 41394771, 2025).
Sertoli Cell-Only Syndrome (1 paper, 2025). A type of male infertility in which no germ cells are visible in any of the biopsied SEMINIFEROUS TUBULES (type I) or in which germ cells are present in a minority of tubules (type II). "Mutations in RBBP7 and RBMXL3 led to Sertoli cell-only syndrome (SCOS)." (PMID 39932629, 2025).
tauopathy (1 paper, 2021). Neurodegenerative disorders involving deposition of abnormal tau protein isoforms (tau proteins) in neurons and glial cells in the brain. "Collectively, our results highlight a novel role of Rbbp7 and set the stage for the development of future therapies to ameliorate tau pathology associated with tau acetylation in AD and related tauopathies." (PMID 33978814, 2021). "Collectively, our results illustrate a novel role of Rbbp7 in protecting against tau pathology, which has significant therapeutic implications for AD and related tauopathies." (PMID 33978814, 2021). "Collectively, these data identify a novel role of Rbbp7, protecting against tau-related pathologies, and highlight its potential as a therapeutic target in AD and related tauopathies." (PMID 33978814, 2021). "Given this protein interaction, Rbbp7 may play a vital role in regulating p300-induced tau acetylation and subsequent tau pathogenesis in AD and related tauopathies." (PMID 33978814, 2021). "While Rbbp7 has been identified to play a role in chaperoning chromatin remodeling proteins, it has yet to be determined whether it plays a direct role in AD and related tauopathies." (PMID 33978814, 2021). "Rbbp7 overexpression protects against cell death in immortalized hippocampal cells, primary cortical neurons and in the PS19 mouse model of tauopathy." (PMID 33978814, 2021). "Here, we interrogate Rbbp7 in post-mortem human brain tissue of patients with AD versus age-matched controls, immortalized hippocampal cells and primary cortical neuron lines, and modulate its expression in the PS19 mouse model of tauopathy." (PMID 33978814, 2021).
testicular tumors (1 paper, 2023). "Our results suggest that X-linked RBBP7 is crucial for spermatogenesis, and its deficiency can lead to inherited predisposition to MA, as well as the potential development of testicular tumors." (PMID 37843278, 2023). "Our results suggest that X-linked RBBP7 is crucial for spermatogenesis, and its deficiency can lead to inherited predisposition for MA, as well as the potential development of testicular tumors." (PMID 37843278, 2023). "In LCT specimens of the proband, low levels of BRCA1 and RBBP7 were observed, leading to an impaired DSB repair system and increased risk for testicular tumor development." (PMID 37843278, 2023). "Further studies are required to verify the frequency of pathogenic variants of RBBP7 in patients with NOA, and special attention should be paid toward screening for possible RBBP7 mutation–related testicular tumors." (PMID 37843278, 2023). "The involvement of RBBP7 in testicular tumors has not been previously reported to our knowledge." (PMID 37843278, 2023).
cancer (16 papers, 2015 to 2025). A tumor composed of atypical neoplastic, often pleomorphic cells that invade other tissues. "Pan-cancer analyses from the single-cell level indicated that RBBP7 and YEATS2 were both associated with multiple cancer functional statuses, re-confirming the vital roles of these genes in the initiation and progression of malignant cancers." (PMID 36503492, 2022). "RBBP7 functions as a subunit of a variety of chromatin-related complexes in epigenetic regulation and is associated with many cancers." (PMID 35884444, 2022). "Therefore deciphering the association between CDK4 and RBBP7 may provide a promising method for cancer treatment." (PMID 35538026, 2022). "RBBP7 is a key element of several complexes for chromatin remodeling and histone modification, that is upregulated in numerous types of cancer and plays contradictory roles in tumors development." (PMID 38645487, 2024). "Previous studies have correlated the overexpression of RBBP4 and RBBP7 with tumor cell proliferation in certain cancer types." (PMID 34086947, 2021). "RBBP7, on the other hand, exhibited high selectivity in terms of cancer cell line dependency, reinforcing the concept of orthologue-specific functions for RBBP4 and RBBP7." (PMID 34086947, 2021). "RBBP7 can specifically bind to the BRCT domain of BRCA1 and modulate its transcriptional activity to influence the regulation of cell proliferation and differentiation, and have been implicated in numerous cancers." (PMID 40688406, 2025). "RBBP7 expression was significantly upregulated in most cancers." (PMID 38368381, 2024). "In several cancers, knockdown of RBBP7 inhibits cell proliferation and metastasis." (PMID 37843278, 2023). "To analyze the RBBP4 and RBBP7 expression levels and correlation with cancer prognosis, we utilized archived patient RNA-seq data from ‘The Cancer Genome Atlas’ (TCGA), focusing on multiple tumor types for which the corresponding normal tissue data were available." (PMID 34086947, 2021). "As such, it is not surprising that RBBP4 and RBBP7 have been extensively implicated in many cancers and are now being pursued as valuable drug targets (reviewd by 24)." (PMID 34086947, 2021). "As an epigenetic factor, RBBP7 binds to histone deacetylase 1 (HDAC1) and specificity protein 1 (Sp1) to exert complicated and contradictory functions in cancer development." (PMID 35538026, 2022). "Retinoblastoma-binding protein 7 (RBBP7) is a core component of many complexes for chromatin remodeling and histone modification, which is overexpressed in many kinds of cancers and exerts conflicting roles in tumor progression." (PMID 35538026, 2022). "Previous studies indicated that BAP1 might inhibit cancer cell growth by interacting with one or more partner proteins, including YY1, RBBP7, HCF-1, H2A, ASXL1/2, and FoxK1/K2." (PMID 40688406, 2025). "Retinoblastoma-binding protein 7 (RBBP7), an important component of chromatin metabolism-regulating complex, is overexpressed in various cancer types, enhancing cancer cell proliferation, invasion and stemness, increasing cyclin-dependent kinase 4 (CDK4) expression." (PMID 38067326, 2023). "Putative cancer drivers with a propensity to carry clonal SCNAs were an android receptor gene, the RNA gene XIST, the BRCA1 binding partners RBBP7 and NCOA2, a BRCC3 metaloprotease unit of the BRISC complex and CSTF2 that prevents inappropriate RNA processing at sites of DNA repair." (PMID 26632267, 2015). "Although there has been considerable research focusing on the role of RBBP4/7 in cancer, studies on targeted therapy for RBBP4 are still very sparse, and no successful targeting of RBBP7 has been reported." (PMID 38028543, 2023).
tumor (15 papers, 2015 to 2024). "Deficiencies in RepID, CRL4 or RBBP7 delay mitotic exit, increase genomic instability and enhance sensitivity to paclitaxel, a microtubule stabilizer and anti-tumor drug." (PMID 31911655, 2020). "Collectively, SP1 facilitated the proliferation of tumor cells and glycolysis in the cells by activating RBBP7, thereby influencing PI3K/AKT signaling." (PMID 38368381, 2024). "Previous studies have reported the role of RBBP7 in tumor initiation and progression although its role in HCC pathogenesis is unclear." (PMID 38368381, 2024). "A dual role of RBBP7 in tumor metastasis has been found to be closely related to recruitment of different RBBP7-containing complexes to EMT-related genes." (PMID 34736517, 2021). "In protein and mRNA level, RBBP7 was higher in tumor group than normal." (PMID 38368381, 2024). "After 33 days, we observed that RBBP7 downregulation could restrict tumor volume and weight compared to the Vector + shNC (P < 0.0001)." (PMID 38368381, 2024). "Single-cell RNA sequencing analyses indicated that RBBP7 and YEATS2 were both associated with the tumor immune response, and the prognosis signature could predict the immunotherapeutic response in two cohorts receiving immunotherapy (P < 0.05; P < 0.01)." (PMID 36503492, 2022). "Interestingly, we observed that YEATS2 was primarily expressed on neutrophils (P < 0.001) and RBBP7 was predominantly expressed in macrophages (P < 0.001), implying both of these genes are involved in tumor immune response of early-stage LUAD." (PMID 36503492, 2022). "RBBP7 could inhibit tumor growth by regulating c-Jun N-terminal kinase (JNK) signal transduction and function as a tumor suppressor gene." (PMID 35538026, 2022). "Furthermore, these high expression levels of RBBP4 and RBBP7 significantly correlated with unfavorable clinical outcomes (P ≤ 0.05) in many tumor types." (PMID 34086947, 2021). "This study examined the role of RBBP7 in HCC progression by evaluating its regulatory effects on glycolysis and tumor cell proliferation." (PMID 38368381, 2024). "RBBP7 mediated the Warburg effect through the PI3K/AKT signaling, which is a crucial pathway for tumor metabolism." (PMID 38368381, 2024). "RBBP7 knockdown downregulated the levels of ATP, lactic acid production, and glucose uptake in HCC, altering the favorable conditions for tumor cell proliferation." (PMID 38368381, 2024). "CPTP was found to be involved in pyroptosis, and while its pro-tumor function in DLBCL was discovered in our study, HTRA1, RBBP7, NFE2L2 and SCAF11 were found to be tumor suppressive." (PMID 36551263, 2022). "Up-regulated RBBP7 was identified as one of the most prominent survival-related genes, which is negatively correlated with the overall survival (OS), disease recurrence-free survival (DFS), and tumor stages." (PMID 35538026, 2022). "FBXL19-AS1 might act as the inducible endogenous RNA of hsa-miR-20b-5p to influence the expression of BTG3, KIF23, RBBP7, and TRIM37 and regulate tumorigenesis, Wnt/β-catenin pathway, tumor metastasis as well as apoptosis." (PMID 33344260, 2020).
adenocarcinoma (1 paper, 2016). A common cancer characterized by the presence of malignant glandular cells. "RBBP7, which was down-regulated on proteome level in adenocarcinoma had also significantly lower gene expression in adenocarcinoma tissues." (PMID 26930711, 2016).
RBBP7 also shares sentences with these, for which no sentence is quoted: Alzheimer disease (2 papers); stomach adenocarcinoma (2); benign tumors (1); bladder cancer (1); cholangiocarcinoma (1); cognitive decline (1); colon adenocarcinoma (1); colorectal adenocarcinoma (1); colorectal cancer (1); Cryptozoospermia (1); dermatomyositis (1); esophageal squamous cell carcinoma (1); glioblastoma multiforme (1); head and neck squamous cell carcinoma (1); leiomyoma (1); lung adenocarcinoma (1); lung squamous cell carcinoma (1); meningioma (1); Nephropathy (1); non-Hodgkin lymphoma (1); non-small cell lung carcinoma (1); Obesity (1); prostate (1); rectum adenocarcinoma (1); rhabdomyoma (1); SARS-CoV Infections (1); uterine corpus endometrial carcinoma (1); Wilms tumor 1 (1).